PRAME (PRAME nuclear receptor transcriptional regulator)
Diseases named in the same sentence as PRAME in open-access papers (continued):
Sharing a sentence is not in itself a finding about the gene and the disease.
cancer (continued). "Through the SAM calculation process, ACTA1, ASPN, C4orf7, CYP26B1, and PRAME showed statistically significant differences in expressions between early and late stages of cancer in both Asian and non-Asian samples." (PMID 24982892, 2014). "Unlike other cancer-testis antigens whose expression is restricted to testis, the PRAME gene shows low level expression in other normal tissues including endometrium, ovary and placenta." (PMID 23460923, 2013). "Unlike the cancer cells in which the PRAME protein was localized in the nucleus, the mouse PRAMEL1 was first seen in the cytoplasm of spermatocytes in 2-week-old testes in this study." (PMID 23565261, 2013). "The mechanism of PRAME expression in malignant tumors has not yet been elucidated in detail." (PMID 38132219, 2023). "PRAME was, until recently, not considered a candidate target for antibody therapy, as monoclonal antibodies exclusively bind to the cell surface and extracellular antigens, while cancer testis antigens are intracellular antigens." (PMID 31311081, 2019).
hematological malignancies (9 papers, 2017 to 2025). "In contrast, a number of reports have suggested that increased PRAME expression is associated with a favorable outcome and treatment response in various hematological malignancies." (PMID 31311081, 2019). "Preferentially Expressed Antigen in Melanoma (PRAME) is a cancer/testis antigen that is found in many solid and hematologic malignancies." (PMID 35076507, 2021). "Furthermore, PRAME is significantly increased in diverse hematologic malignancies, including acute and chronic leukemias, non-Hodgkin’s lymphomas, and multiple myeloma, distinguishing it from the majority of other tumor-associated antigens (TAAs)." (PMID 38596687, 2024). "We hypothesized that PRAME might have value as a molecular “fingerprint” to help with this distinction given its correlation with disease progression in other hematologic malignancies." (PMID 35076507, 2021). "PRAME has been shown to be overexpressed in an array of solid and hematological malignancies." (PMID 29029482, 2017).
hematological cancers (3 papers, 2019 to 2023). "PRAME re-expression has been demonstrated in several solid and hematological cancers, driving clinical trials investigating PRAME as an immunotherapeutic target." (PMID 30602372, 2019).
bacterial infection (1 paper, 2013). "Taken together, these results indicate that, similar to genes encoding other LRR proteins such as NALPs and TLRs, PRAME expression in HL60 cells may be rapidly induced by signalling pathways activated in response to bacterial infection/inflammation." (PMID 23460923, 2013).
infection (1 paper, 2013). The state of being infected such as from the introduction of a foreign agent such as serum, vaccine, antigenic substance or organism. "Thus, PRAME is upregulated by signalling pathways that are activated in response to infection/inflammation, and its product may have dual functions as a histone-binding protein, and in directing ubiquitylation of target proteins for processing in the Golgi." (PMID 23460923, 2013).
PRAME also shares sentences with these, for which no sentence is quoted: acute lymphoblastic leukemia (6 papers); renal cell carcinoma (4); laryngeal squamous cell carcinoma (3); multiple myeloma (3); superficial spreading melanoma (3); adenocarcinoma (2); basal cell carcinoma (2); malignant peripheral nerve sheath tumor (2); mantle cell lymphoma (2); melanocytic nevus (2); myelodysplastic syndrome (2); myxoid/round cell liposarcoma (2); spindle cell melanoma (2); undifferentiated pleomorphic sarcoma (2); astrocytic tumor (1); B-cell acute lymphoblastic leukemia (1); basal cell skin carcinomas (1); blue nevus (1); bone sarcoma (1); Bowen's disease (1); brain tumors (1); cervical tumor (1); chronic leukemia (1); clear cell sarcoma (1); CNS tumors (1); colon cancer (1); colorectal cancer (1); dedifferentiated liposarcoma (1); endometrial cancer (1); esophageal squamous cell carcinoma (1).
A further 37 diseases each share a sentence with PRAME in 1 paper.